CRIPTOP5 (CRIPTO pseudogene 5)
Synonyms: CR-5; CRIPTO-5; formerly TDGF5; TDGF1P5
Gene: Processed pseudogene on chromosome 8 (54,073,114 to 54,073,566, forward strand). Ensembl gene ENSG00000254274.
Diseases named in the same sentence as CRIPTOP5 in open-access papers:
CRIPTOP5 is named in the same sentence as 6 diseases in open-access papers, as found by Europe PMC text mining. Sharing a sentence is not in itself a finding about the gene and the disease.
CRIPTOP5 shares sentences with these, for which no sentence is quoted: infection (2 papers); aging (1); dyskeratosis congenita (1); neutropenia (1); skin aging (1); tumor (1).